MMP3 (matrix metallopeptidase 3)
Diseases named in the same sentence as MMP3 in open-access papers (continued):
Sharing a sentence is not in itself a finding about the gene and the disease.
Obesity (continued). "MMP-3, MMP-7, and MMP-12 polymorphisms associate with obesity risk and its severity." (PMID 29317790, 2017). "Together, these data demonstrate that obesity is responsible for MMP3-induced MMP9 activation in tumor patients and this process may be mediated by exosomes." (PMID 29137230, 2017). "A similar finding was obtained in both obese and morbidly obese subjects, suggesting that MMP-3 Lys45Glu variant could affect MMP-3 protein expression and is therefore related to obesity development and severity." (PMID 29317790, 2017). "According to the literature, alterations of MMP-3 pathway in obesity could be related to functional SNPs in MMP-3 gene." (PMID 29317790, 2017). "According to the literature, MMP-3 could also be related to low-grade chronic inflammation in obesity." (PMID 29317790, 2017). "Obesity was also associated with increased expressions of angiogenesis-related proteins, in particular, angiogenin, endoglin, endostatin, endothelin-1, IGFBP-3, leptin, MMP-3, PAI-1, TIMP-4, CXCL16, platelet factor 4, DPPIV and coagulation factor III." (PMID 22748184, 2012). "Furthermore, attenuation of MMP-3 was observed in the adipose tissue of retinoic acid receptor orphan mice, which is related to increased adipogenesis and improved insulin sensitivity in a diet-induced obesity model." (PMID 37372128, 2023). "Finally, we want to know whether obesity could affect MMP3 protein levels and MMP9 activity in lung tumor tissues." (PMID 29137230, 2017). "No studies have explored, however, the impact of MMP-3 Lys45Glu variant on obesity status." (PMID 29317790, 2017). "In ANOVA modeling, leptin concentrations in SF and SOCS-3 expression in cartilage significantly explained levels of SF MMP-1 and MMP-3 in the obese but not in the non-obese group pointing to obesity-related association of leptin and SOCS-3 in OA pathophysiology." (PMID 27716333, 2016). "It has been suggested that macrophage accumulation in adipose tissue has a central role in stimulating MMP1 and MMP3 production by preadipocytes, mediated by IL1β and TNFα, supporting the role of macrophages in stimulating tissue remodeling during adipose tissue expansion in obesity." (PMID 23497408, 2013). "The level of both metalloproteinases was significantly higher in patients with a DM2 history longer than 10 years (MMP-3 = 125.7 pg/mL; MMP-9 = 2307.5 pg/mL) and in diabetic patients with obesity (MMP-3 = 128.6 pg/mL; MMP-9 = 2160.9 pg/mL)." (PMID 36362386, 2022). "In conclusion, our results demonstrated that MMP-1, MMP-3 and MMP-9 levels were correlated with several obesity-related parameters including BMI, WC, blood pressure and endothelial-dependent response." (PMID 34625635, 2021). "Among MMPs, MMP-1, MMP-3, MMP-7, and MMP-12 genes have been found to affect adipose tissue remodeling and obesity-related metabolic traits." (PMID 29317790, 2017). "The goals of the current report were to explore the impact of MMP-1 (-519A/G; -1607 1G/2G), MMP-3 Lys45Glu (A/G), MMP-7 -181A/G, and MMP-12 -82A/G SNPs on the development of obesity and its severity among Tunisians." (PMID 29317790, 2017). "This study sought to determine the responses in circulating APN, MMP-2, MMP-3 and OPN—key proteins involved in the remodelling of adipose tissue —following two different exercise formats in individuals with overweight or obesity." (PMID 36648516, 2023). "In contrast, in the E0771-bearing C57BL/6 mouse model, obesity not only led to an increase in ECM1 protein levels within sEVs, but it also resulted in a significant elevation of tumor ECM1 protein levels, as well as the downstream proteins MMP3 and S100A/B, compared to CD mice." (PMID 38402239, 2024). "However, in two animal models of genetic obesity (ob/ob and db/db) and in a HFD model, while mRNA levels for MMP2, MMP3, MMP12, MMP14, MMP19, and TIMP1 are robustly induced, MMP7 (and MMP3) transcripts are markedly reduced in obese visceral adipose tissue compared to lean tissue." (PMID 37445827, 2023).
endometriosis (23 papers, 2013 to 2025). The growth of functional endometrial tissue in anatomic sites outside the uterine body. "MMP3 remodels extracellular matrix and is overexpressed in endometriosis, and MMP3 polymorphism increases the risk of developing advanced endometriosis and infertility." (PMID 39836475, 2025). "In women with endometriosis, polymorphisms in MMP3 have been linked to an enhanced risk of developing advanced endometriosis and infertility, while polymorphism in MMP12 is associated with the development of superficial endometriosis." (PMID 39385609, 2024). "The over-expression, enhanced secretion, and activity of MMP2 and MMP3 has previously been implicated in pathogenesis of endometriosis." (PMID 36551177, 2022). "Particularly, MMPs are involved in cyclic changes of the endometrial structure and thickness during menstruation and dysregulation of MMP2, and MMP3 has previously been implicated in the pathogenesis of endometriosis." (PMID 36551177, 2022). "Increased levels of MMP-1, MMP-2, and MMP-3 in endometriotic lesions indicate that endometriosis may have a unique metabolomic signature linked to cell cycle arrest and inflammation." (PMID 40834152, 2025). "The increased levels of MMP-1, MMP-2, and MMP-3 in endometriotic lesions observed in this study indicate that endometriosis may have a distinct metabolomic signature linked to cell cycle arrest and inflammation." (PMID 40834152, 2025). "Both MMP2 and MMP3 have been implicated in the pathogenesis of endometriosis." (PMID 35453712, 2022). "Curcumin could act as an inhibitor of NF-κB and MMP-3 by influencing signaling pathways and increasing the secretion of associated proteins in human endometriotic stromal cells, thus mediating the regression of endometriosis." (PMID 30402122, 2018). "The deregulation of miR-93 is believed to contribute to endometriosis by upregulating MMP3 and VEGFA, suggesting potential therapeutic targets." (PMID 40305232, 2025). "The association of MMP-1 and MMP-3 with the SASP and endometriosis pathophysiology prompted us to investigate the levels of these ECM components in our samples using the Luminex xMAP technology." (PMID 40834152, 2025). "MMP3 expression appeared strongest in both endometriosis and control samples during the secretory stage with a slightly more prevalent expression in the endometriosis compared with control samples." (PMID 35725766, 2022). "They demonstrated a potent inhibitory effect of simvastatin on the development of endometriosis and on matrix metalloproteinase-3 (MMP-3)." (PMID 28950844, 2017). "The overall conclusion is that the increase of uPA and MMP-3 in the endometrium of women with endometriosis leads in an increase in the invasive capacity of endometriosis cells." (PMID 24294950, 2013). "The increased levels of MMP-2 and MMP-3 in endometriotic lesions compared with those in the eutopic and control endometrium could be a distinct metabolomic signature in endometriosis, potentially resulting from cell cycle arrest." (PMID 40834152, 2025). "Interestingly, Il6, Mmp3, Itgb2, and Vegfa, a group of genes known to play a role in endometriosis, increased in the developing lesion tissues in all groups compared with control I and α minced endometrial pieces." (PMID 39836475, 2025). "Interestingly, we found that Mmp3 expression dramatically increased in endometriosis lesion tissue and that fibrinogen was the preferred substrate for endometrial cell adhesion." (PMID 39836475, 2025). "Elevated levels of MMP-3 have been observed in animal models with induced endometriosis." (PMID 33804660, 2021). "SASP gene products identified by RNAseq include many inflammatory biomarkers that have been historically analyzed in endometriosis, including IL-1β, IL-6, IL-8, CCL5, TNF-α, CCL2, MMP3, HMGB1, p16, and p21." (PMID 38879630, 2024). "Other studies also showed that the expression levels of MMP2, MMP3, and MMP9 in ectopic endometrium and endometriosis cells were amplified." (PMID 36235740, 2022).
endometriosis (continued). "In order to clarify the role of metalloproteases and their inhibitors in endometriosis development, MMP2, MMP3, MMP10, TIMP1, and TIMP2 expression was measured in healthy and eutopic endometrium, in OMA and DIE lesions." (PMID 32325785, 2020). "In vitro studies reported an increased MMP-3 and MMP-7mRNA expression in the eutopic endometrium of women affected by endometriosis in the secretory phase." (PMID 31717614, 2019). "In the literature, miR-93 (the precursor of miR-93-5p) has been shown to target Matrix Metalloproteinase 3 (MMP3) and Vascular Endothelial Growth Factor A (VEGF-A), which are involved in endometriosis by contributing to tissue remodeling, angiogenesis, and the proliferation of endometriotic lesions." (PMID 40305232, 2025). "These cells showed changes in growth profiles, were characterized by high expression of matrix metalloproteinases (MMP) MMP3 and MMP10, and may have a role in endometriosis etiology." (PMID 36746607, 2023). "Moreover, the increased expression and activity of MMPs such as MMP2, MMP3, and MMP9 has been reported in endometriosis." (PMID 36551177, 2022). "Our immunofluorescent analysis of endometrial samples from women with and without endometriosis supported a focal expression of MMP3 with a more pronounced expression in the secretory stage and in women with endometriosis." (PMID 35725766, 2022). "Aberrant regulation of MMPs such as MMP2, MMP3, and MMP9 has been reported in endometriosis." (PMID 35453712, 2022). "Xiaozheng decoction also could relieve dysmenorrhea and pelvic pain and improve qi stagnation and blood removal in endometriosis patients, which may be related to lower levels of CA125, CA199, MMP-3, MMP-9, VEGF, and TNF-α in serum." (PMID 30402122, 2018). "A similar fibroblast signature characterized by MMP3 and MMP10 was observed in menstrual fluid of patients with endometriosis, suggesting these altered fibroblasts may be maintained during menstruation and may represent a possible non‐invasive diagnosis signature." (PMID 36746607, 2023).
chondrosarcoma (22 papers, 2005 to 2024). A malignant cartilaginous matrix-producing mesenchymal neoplasm arising from the bone and soft tissue. "Earlier we reported CCL5 enhancing chondrosarcoma migration and metastasis via matrix metalloproteinase-3 (MMP-3) up-regulation." (PMID 25301739, 2014). "In order to check the eotaxin-1-induced MMP-3 protein levels in chondrosarcoma cells, we performed Western blotting using cell lysates and culture media." (PMID 22114952, 2011). "There were studies showing the involvement of PLC in gene regulation of MMP-3 in fibroblasts and other MMPs in chondrosarcoma cells." (PMID 22114952, 2011). "The production of eotaxin-1 not only induces expression of its own receptors, CCR3 and CCR5, on the cell surface of chondrosarcomas, but also markedly increases the expression of MMP-3 mRNA in chondrocytes." (PMID 22114952, 2011). "The PKA inhibitor also increased the effects of eotaxin-1 by inducing MMP-3 transcription in chondrosarcoma cells." (PMID 22114952, 2011). "It is notable that treatment with eotaxin-1 alone was able to induce MMP-3 expression in both primary chondrocytes and a chondrosarcoma cell line." (PMID 22114952, 2011). "More recently, RANTES has been shown to enhance the migration of chondrosarcoma cells through increased MMP-3 production." (PMID 20442771, 2010). "This study aims to suppress the expression of the MMP-3 gene in in vitro human chondrosarcoma using siRNA." (PMID 20034400, 2009). "Furthermore, CCL5 stimulates cell migration through the activation of matrix metalloproteinase-3 (MMP-3), thus aiding in the metastasis of chondrosarcoma." (PMID 38542153, 2024). "CCL5 reportedly promotes migration and metastasis in human chondrosarcoma by up-regulating MMP-3." (PMID 25301739, 2014). "Similarly in the present study, we demonstrated that MMP-3 expression in SW1353 chondrosarcoma cells and primary chondrocytes was obviously induced by eotaxin-1 at 30 and 10 ng/ml, respectively." (PMID 22114952, 2011). "MMP-3 specific siRNA can inhibit the expression of MMP-3 in chondrosarcoma." (PMID 20034400, 2009). "Based on the cell apoptosis result, MMP-3 suppression could decrease chondrosarcoma apoptosis significantly." (PMID 20034400, 2009). "This study demonstrated that NUC1 inhibited the production of NO in LPS-induced macrophages, and reduced MMP-1, MMP-3, and MMP-13 levels in chondrosarcoma cells treated with TNF-α." (PMID 37482815, 2023). "Our results showed that NUC1 treatment inhibited the extracellular release of MMPs by blocking TNF-α-induced MMP-1, MMP-3, and MMP-13 expression in chondrosarcoma cells." (PMID 37482815, 2023). "Whilst downregulation of MMP3 and MMP13 has been reported to be indicative of the chondroprotective action of Icariin in SW1353 chondrosarcoma cells stimulated with IL-1β." (PMID 33177241, 2020). "Relative to the levels for IL-1β-treated human chondrosarcoma cell line SW1353, the expressions of MMP-1, MMP-3 and MMP-13 were decreased dose dependently in the 20 μg/mL CZE and 0.4 μg/mL linarin treatment." (PMID 33321982, 2020). "The increases in IL-1β-treated human chondrosarcoma cell line SW1353 were 65.6% for MMP-1, 196.5% for MMP-3 and 119.3% for MMP-13." (PMID 33321982, 2020). "We first verified that transcriptional expression of MMP1, MMP3, MMP13, and ADAMTS4 was upregulated by IL-1β or TNF-α and repressed by I-BET151 in a human chondrosarcoma cell line (SW1353)." (PMID 30786900, 2019). "In consideration of semi quantitative scoring 64% of chondrosarcoma were scored as positive for MMP-1, 46% for MMP-3, 61% for MMP-9." (PMID 29316907, 2018). "rCCL5 induced MMP-3 expression and migration via phosphatidylinositol 3-kinase (PI3K), v-Akt murine thymoma viral oncogene homolog (AKT) and NF-κB in the same chondrosarcoma cell line." (PMID 29361725, 2018). "The purpose of this study was to investigate immunohistochemicaly the influence of MMP-1, MMP-3, MMP-9 and MMP-13 expression on prognostic parameter in chondrosarcoma." (PMID 29316907, 2018).
chondrosarcoma (continued). "We previously reported that CCL5 enchances cell migration through activation of matrix metalloproteinase-3 (MMP-3) and promotes VEGF-A-dependent tumor angiogenesis in human chondrosarcoma, implying that CCL5 is involved in the metastasis of chondrosarcoma." (PMID 27166194, 2016). "Our early study highlighted CCN1 activated MMP-3 expression and cell migration through αvβ3 receptor and FAK/ERK/AP-1 in human chondrosarcoma." (PMID 25187949, 2014). "Studies have shown that MMP-1, MMP-2, MMP-3, MMP-9, and MMP-13 exhibit high degrees of expression in human chondrosarcoma cells." (PMID 23892595, 2013). "It was also recently published that A-SAA increased MMP-1, MMP-3 and MMP-13 mRNA and protein expression levels on human chondrosarcoma cells SW1353 and human primary chondrocytes provided from normal articular cartilage." (PMID 23776697, 2013). "A previous study showed that MMP-1, MMP-2, MMP-3, MMP-9, and MMP-13 were expressed in high quantities in human chondrosarcoma cells." (PMID 23892595, 2013). "MMP-3 and MMP-13 gene expression induced by IL-1β, TNF-α and IL-17 was downregulated by mithramycin in human chondrosarcoma SW1353 cells and in primary human and bovine femoral head chondrocytes." (PMID 15987479, 2005). "MMP-1 and MMP-3 expression in IL-1β-stimulated chondrosarcoma cells was suppressed by p38 and ERK inhibitors but not by JNK inhibitor, and MMP-13 expression was suppressed by p38 and JNK inhibitors but not ERK inhibitor." (PMID 32213810, 2020). "Here, we showed that AG1478 treatment of HEMC-SS chondrosarcoma cells inhibits the expression of MMP-13 and MMP-3, suggesting that inhibition of EGFR may impair metastatic potential of chondrosarcoma." (PMID 31139331, 2019). "MMP-1, MMP-2, MMP-3, MMP-7, MMP-9 and MMP-13 are frequently expressed in chondrosarcoma tissues." (PMID 29361725, 2018). "In conclusion, MMP-1, MMP-3 and MMP-9 are often expressed in chondrosarcoma." (PMID 29316907, 2018). "The increase in MMP-13 expression may be necessary for the activation of other MMPs that have previously been identified in chondrosarcoma such as MMP-2 and MMP-9 it is also activated by MMP-2, MMP-3, and MTI-MMP." (PMID 18554405, 2008). "In consideration of semiquantitative scoring 64% of chondrosarcoma were scored as positive for MMP-1, 46% for MMP-3, 61% for MMP-9 and no for MMP-13." (PMID 29316907, 2018).